RNU6-1281P (RNA, U6 small nuclear 1281, pseudogene)
Gene: Small nuclear RNA gene on chromosome 1 (51,538,625 to 51,538,729, reverse strand). Ensembl gene ENSG00000252032.
Homologues: Orthologues: macaque U6 (91% identical), rabbit RNU6-1281P (80% identical), guinea pig U6 (70% identical), pig U6 (65% identical). Paralogues in human: RNU6-16P (79% identical), RNU6-1251P (78% identical), RNU6-812P (78% identical), RNU6-1145P (77% identical), RNU6-38P (77% identical), RNU6-441P (77% identical), RNU6-59P (77% identical), RNU6-616P (77% identical), RNU6-618P (77% identical), RNU6-639P (77% identical), RNU6-836P (77% identical), RNU6-1 (76% identical), and 1286 more.